CBR1 (carbonyl reductase 1)
Description:
NADPH-dependent reductase with broad substrate specificity. Catalyzes the reduction of a wide variety of carbonyl compounds including quinones, prostaglandins, menadione, plus various xenobiotics. Catalyzes the reduction of the antitumor anthracyclines doxorubicin and daunorubicin to the cardiotoxic compounds doxorubicinol and daunorubicinol. Can convert prostaglandin E to prostaglandin F2-alpha (By similarity). Can bind glutathione, which explains its higher affinity for glutathione-conjugated substrates. Catalyzes the reduction of S-nitrosoglutathione. In addition, participates in the glucocorticoid metabolism by catalyzing the NADPH-dependent cortisol/corticosterone into 20beta-dihydrocortisol (20b-DHF) or 20beta-corticosterone (20b-DHB), which are weak agonists of NR3C1 and NR3C2 in adipose tissue.
Synonyms: PG-9-KR; CBR; SDR21C1; hCBR1
Tractability: Small molecule: a structure with a bound ligand is known; a high-quality ligand is known; it has a high-quality binding pocket; it belongs to a druggable protein family. PROTAC: ubiquitination databases record sites on it; its protein half-life has been measured; a small molecule that binds it is known.
Target class: Enzyme; Oxidoreductase
Safety:
Unwanted effects reported when the protein is acted on. In parentheses: how it was acted on, where the effect was seen, and who reports it.
cardiomyopathies (source: ClinPGx)
vomiting (source: ClinPGx)
Gene: Protein-coding gene on chromosome 21 (36,069,941 to 36,073,166, forward strand). Ensembl gene ENSG00000159228.
Subcellular location: Cytoplasm
Subcellular location (Human Protein Atlas): Nucleoplasm; Cytosol
Pathways (Reactome):
Metabolism: Synthesis of Prostaglandins (PG) and Thromboxanes (TX)
Gene Ontology:
Molecular function: 15-hydroxyprostaglandin dehydrogenase (NADP+) activity; alcohol dehydrogenase (NADP+) activity; carbonyl reductase (NADPH) activity; oxidoreductase activity, acting on NAD(P)H, quinone or similar compound as acceptor; oxidoreductase activity, acting on the CH-OH group of donors, NAD or NADP as acceptor; prostaglandin E2 9-reductase activity; protein binding; S-nitrosoglutathione reductase (NADPH) activity; 15-hydroxyprostaglandin-D dehydrogenase (NADP+) activity; alcohol dehydrogenase [NAD(P)+] activity; NADPH dehydrogenase (quinone) activity
Biological process: epithelial cell differentiation; glucocorticoid metabolic process; positive regulation of reactive oxygen species metabolic process; vitamin K metabolic process; xenobiotic metabolic process; prostanoid biosynthetic process
Cellular component: cytosol; extracellular exosome; extracellular vesicle; cytoplasm
Genetic constraint (gnomAD): Loss-of-function variants: 13 observed, 14.54 expected, observed/expected ratio (o/e) 0.89, 90% interval 0.58 to 1.42. The upper end of that interval is the gene's LOEUF score, 1.42, which puts it in group 5 of 6, group 1 being the genes least tolerant of losing a copy. Missense variants: 360 observed, 372.66 expected, observed/expected ratio (o/e) 0.97, 90% interval 0.88 to 1.05. Synonymous variants: 158 observed, 154.47 expected, observed/expected ratio (o/e) 1.02, 90% interval 0.9 to 1.17.
Homologues: Orthologues: chimpanzee CBR1 (100% identical), mouse Cbr1 (88% identical), rat Cbr1l3 (85% identical), pig CBR1 (84% identical), mouse Cbr1b (84% identical), dog CBR1 (81% identical), tropical clawed frog cbr1.3 (73% identical), zebrafish cbr1 (66% identical), Drosophila melanogaster CG31548 (19% identical), Caenorhabditis elegans F20G2.2 (18% identical), Caenorhabditis elegans dhs-6 (18% identical), Caenorhabditis elegans F20G2.1 (18% identical), and 8 more. Paralogues in human: CBR3 (72% identical), DHRS4 (24% identical), HSDL2 (22% identical), DHRS2 (22% identical), DHRS1 (20% identical), DHRS7 (19% identical), DHRS4L2 (19% identical), DHRS7B (19% identical), DHRS11 (18% identical), DHRS7C (18% identical), RDH8 (18% identical), HSD11B1 (18% identical), and 1 more.
Diseases named in the same sentence as CBR1 in open-access papers:
CBR1 is named in the same sentence as 77 diseases in open-access papers, as found by Europe PMC text mining. Sharing a sentence is not in itself a finding about the gene and the disease. The quoted sentences say what the papers report.
breast carcinoma (9 papers, 2014 to 2025). "Associations of AKR1C2, AKR7A3, and CBR1 with prognosis of breast carcinoma patients revealed by this study should be further followed in independent validation and functional studies." (PMID 25526449, 2014). "Previous studies have reported that blocking CBR-1 signaling inhibits cancer growth in mantle cell lymphoma, thyroid, colon, and breast cancers in vitro and in vivo." (PMID 39707578, 2024). "In the present study, we aimed to evaluate CBR1 and CBR2 expression in breast tumours and its association with breast cancer prognostic factors and survival." (PMID 34575629, 2021). "This is the first study to evaluate both CBR1 and CBR2 expression in association with breast cancer prognostic factors and survival." (PMID 34575629, 2021). "CBR1 is correlated with doxorubicin resistance in human gastrointestinal cancer, and the efficacy of doxorubicin can be improved by inhibiting CBR1 in breast cancer treatment." (PMID 29957874, 2018). "Mechanisms of action of AKR1C2, AKR7A3, CYP2B6, CYP3A4, and CBR1 should continue to be further followed in breast carcinoma patients and models." (PMID 25526449, 2014). "In addition to this, CBR1 has also been implicated in DDR activities such as protecting cellular survival via the NRF2 pathway, as well as oncogenic activity in breast cancer." (PMID 37239845, 2023). "Furthermore, inhibition of CBR1 safely improves the efficacy of doxorubicin in breast cancer treatment." (PMID 35957912, 2022). "Therefore, in the present study, we aim to evaluate CBR1 and CBR2 expression in breast tumours and their association with breast cancer prognostic factors and survival." (PMID 34575629, 2021). "CBR1 (carbonyl reductase 1) may reduce the effect of many anti-cancer drugs by metabolization, such as reducing the effect of doxorubicin in breast cancer patients and attenuating the effect of arsenic trioxide in leukemia patients." (PMID 27690302, 2016). "Thus, CBR1 presents another candidate for functional verification in breast carcinoma models." (PMID 25526449, 2014). "The stabilization of HIF-1 also increases the expression of carbonyl reductase 1 (CBR1) in hypoxic hepatocellular carcinoma cells and MCF-7 breast cancer cells." (PMID 36551540, 2022). "Our results indicate that CBR1 and CBR2 may have different involvement in breast cancer progression." (PMID 34575629, 2021). "While no previous study has examined the expression of CBR1 in breast cancer, the single previous study that evaluated CBR2 expression in breast cancer reported that high CBR2 expression in HER2 positive tumours was associated with poor prognosis." (PMID 34575629, 2021). "However, direct evidence linking RIMS1, IK, SF3B1, and CBR1 genes specifically to lactylation modifications in breast cancer is lacking." (PMID 40406140, 2025). "Gene expression of 13 aldo-keto reductases (AKRs), carbonyl reductase 1, and 10 cytochromes P450 (CYPs) was assessed using quantitative real-time polymerase chain reaction in tumors and paired adjacent nonneoplastic tissues from 68 posttreatment breast carcinoma patients." (PMID 25526449, 2014).
hepatocellular carcinoma (6 papers, 2018 to 2024). A malignant tumor that arises from hepatocytes. "(−)-epigallocatechin gallate, a promising inhibitor of CBR1, enhanced the antitumor activity of daunorubicinol against hepatocellular carcinoma cells expressing high levels of CBR1 and corresponding xenografts." (PMID 30376862, 2018). "CBR1 overexpression enhanced cell survival by decreasing oxidative stress under hypoxia, cisplatin, and doxorubicin treatment in hepatocellular carcinoma." (PMID 30376862, 2018). "Similarly, Y6, an ethylated derivative of EGCG, was also revealed to significantly inhibit the CBR1 expression in hepatoma cells, thus enhancing the efficacy of daunorubicin against HCC." (PMID 37292151, 2023). "The inhibition of CBR1 activity can enhance the effectiveness and decrease the cardiotoxicity of the anticancer drug anthracycline daunorubicin (DNR) in hepatocellular carcinoma." (PMID 33072014, 2020). "However, considering the lack of expression of HSD11B1 and CBR1 in human hepatoma cells, the potential contribution of these enzymes in cortisone metabolism, resulting in differences in the proportion of the 5β-reduced product, may be small, but cannot be excluded." (PMID 31330134, 2019).
pancreatic cancer (6 papers, 2017 to 2024). "Chrysin induces autophagy-dependent ferroptosis to increase chemosensitivity to gemcitabine by targeting CBR1 in pancreatic cancer cells." (PMID 37469162, 2024). "Inhibiting CBR1 activity in gemcitabine-resistant pancreatic cancer to trigger ferroptosis through ROS accumulation." (PMID 38239395, 2023). "HIPK3 has been related to apoptosis resistance, CBR1 has been identified as a patient survival marker, ALDH3A1 and ALDH3A2 have been related to drug response, and NOS1 has been related to pancreatic cancer risk." (PMID 29285214, 2017). "Human carbonyl reductase 1 (CBR1) contributes to gemcitabine resistance in pancreatic cancer." (PMID 38239395, 2023). "In a study, chrysin was found to degrade FTH1 by inhibiting the activity of carbonyl reductase 1(CBR1), which increased the levels of Fe2+ and lipid peroxidation and led to ferroptosis in pancreatic cancer cells." (PMID 37833746, 2023).
depression (5 papers, 2012 to 2025). "Blockade of the most abundant endocannabinoid receptor in the brain, CBR1, causes depression, but chronic activation of CBR1 induces their desensitization." (PMID 37047638, 2023). "At the same time, depression is associated with an increased density of CBR1 in the prefrontal cortex, which is assumed as a compensatory mechanism in response to reduced levels of endocannabinoids." (PMID 37047638, 2023). "Similar studies were performed by another group where they reported the antidepressant activity of CUR-DB SLNs in the wild-type (CBR1+/+) and CB1-knockout (CBR1–/–) mouse models of major depressive disorder." (PMID 37111244, 2023). "Depression of the Nrf2/CBR1 pathway in both mothers and their offspring is one of the causes of oxidative stress leading to MetS." (PMID 32184720, 2020). "Finally, the antidepressant effects of the developed formulation were investigated in wild-type (CBR1+/+) and cannabinoid receptor 1 knockout (CBR1−/−) mouse models of corticosterone-induced major depressive disorder." (PMID 40863840, 2025). "Interestingly, the absence of antidepressant effects in the CBR1−/− mouse model of major depressive disorder suggests that CBR1 is necessary for the effects observed in response to the proposed treatment." (PMID 40863840, 2025).
leukemia (5 papers, 2016 to 2025). A malignant (clonal) hematologic disorder, involving hematopoietic stem cells and characterized by the presence of primitive or atypical myeloid or lymphoid cells in the bone marrow and the blood. "By regulating reactive oxygen species production, elevated expression of CBR1 is able to safeguard leukemia cells against As2O3." (PMID 40584831, 2025). "CBR1 overexpression can also protect leukemic cells from As O23 by regulating reactive oxygen species production while inhibiting CBR1 expression enhances the effect of As O23 on therapeutic sensitivity in a variety of leukemia cell lines." (PMID 38273850, 2023). "CBR1 affects the resistance to arsenic trioxide in leukaemia and CBR1 overexpression was sufficient to protect cells against arsenic trioxide through modulation of the generation of ROS." (PMID 30376862, 2018).
Obesity (5 papers, 2015 to 2024). Accumulation of substantial excess body fat. "In humans, horses and mice obesity was associated with increased CBR1/Cbr1 expression in adipose tissue, in horses with increased 20β-DHF in plasma, and in humans and horses with increased 20β-DHF in urine." (PMID 28878267, 2017). "Although 20β-DHF was not disproportionately raised in urine, total cortisol metabolite excretion was increased so these data are consistent with the CBR1/20β-DHF pathway contributing to increased cortisol clearance in obesity." (PMID 28878267, 2017). "To further explore the contribution of CBR1 dysregulation in obesity, we administered the Cbr1 inhibitor quercetin to mice with diet-induced obesity." (PMID 28878267, 2017). "Murine diet-induced obesity was therefore used as a model in which to investigate the functional role of CBR1 and 20β-dihydro metabolites." (PMID 28878267, 2017). "Pharmacological inhibition of CBR1 in diet-induced obesity in mice results in more marked glucose intolerance with evidence for enhanced hepatic GR signaling." (PMID 28878267, 2017). "CBR1 provides the major route of cortisol metabolism in horses and is up-regulated in adipose tissue in obesity in horses, humans and mice." (PMID 28878267, 2017). "In the obesity study, strong genetic control of body fat set-point as well as microbiome plasticity was unraveled, and multiple genetic loci were identified for obesity traits and dietary responses (e.g., Sptlc3, Klf14, Degs1, Npc, Cbr1, and amylases)." (PMID 26202330, 2015). "The success of CBR1 blocker, rimonabant, in treating obesity was demonstrated in clinical trials." (PMID 39292202, 2024). "Mice lacking one Cbr1 allele and mice overexpressing Cbr1 in their adipose tissue underwent metabolic phenotyping before and after induction of obesity with high-fat feeding." (PMID 33785425, 2021). "We chose to examine the effect of obesity on expression of CBR1 in liver and adipose tissue." (PMID 28878267, 2017). "Moreover, CBR1 is involved in the regulation of tissue glucocorticoid metabolism, glucose homeostasis, and the reduction in lipid peroxidation products, and may contribute to the cardiometabolic complications of obesity." (PMID 39594513, 2024). "Current evidence links human obesity to ECS activation, increased endocannabinoid levels in both central and peripheral tissues, along with cannabinoid receptor type 1 (CBR1) up‐regulation." (PMID 39292202, 2024). "Up-regulation of the CBR1 pathway in obesity was evident in adipose but not liver in horses and mice." (PMID 28878267, 2017). "Hepatic CBR1 mRNA was not altered in obesity in horses or mice but CBR1 mRNA was increased in adipose tissue of obese horses." (PMID 28878267, 2017). "In addition we did not identify any eQTL for CBR1 expression in adipose suggesting that this up-regulation is a functional response to obesity." (PMID 28878267, 2017). "Carbonyl reductase 1 (Cbr1), a recently discovered contributor to tissue glucocorticoid metabolism converting corticosterone to 20β-dihydrocorticosterone (20β-DHB), is upregulated in adipose tissue of obese humans and mice and may contribute to cardiometabolic complications of obesity." (PMID 33785425, 2021). "Therefore, under normal diet conditions, a lack of CBR1 may be beneficial due to a reduction in GR/MR activation by 20β-DHB, but when oxidative stress increases in obesity, its absence is detrimental, cancelling out any protective effects." (PMID 33785425, 2021).
Down syndrome (4 papers, 2017 to 2025). "CBR1, the gene encoding the ubiquitously expressed enzyme carbonyl reductase 1 (CBR1), is located in the ‘Down syndrome critical region’ of chromosome 21, the region that co-segregates with many of the developmental features of DS." (PMID 39869501, 2025). "The study discovered a 1.6-fold increase in CBR1 expression in Down syndrome individuals as well as the fact that this protein is responsible for around 90% of daunorubicin metabolism." (PMID 40362292, 2025).
ovarian carcinoma (4 papers, 2019 to 2024). A malignant neoplasm originating from the surface ovarian epithelium. "Decreased CBR1 expression is associated with a poor prognosis in ovarian cancer; they also investigated the relationship between the level of CBR1 expression and the malignant potential of ovarian cancer." (PMID 33613283, 2020). "A previous study reported that downregulation of CBR1 increased vascular endothelial growth factor (VEGF)-C expression in ovarian cancer cells." (PMID 31942176, 2020). "Several recent reports indicated that CBR1 expression is highly correlated with tumor metastasis in some tumors, including oral squamous cell carcinoma 6, ovarian cancer 7, and endometrial cancer 8, even though the results of some cases were contradictory." (PMID 31942176, 2020). "A previous study demonstrated that low expression of CBR1 promotes growth and proliferation of ovarian cancer." (PMID 31528236, 2019).
head and neck squamous cell carcinoma (3 papers, 2018 to 2020). A squamous cell carcinoma that arises from any of the following anatomic sites: lip and oral cavity, nasal cavity, paranasal sinuses, pharynx, larynx, and salivary glands. "The formalin-fixed and paraffin-embedded tissues of 85 patients with head and neck squamous cell carcinoma (HNSCC) were used to determine if CBR1 expression effects on survival of patients with treatment of radiotherapy." (PMID 30376862, 2018). "However, the detailed mechanism and clinical correlation between CBR1 and tumor progression in head and neck squamous cell carcinoma (HNSCC) is largely unexplored." (PMID 31942176, 2020). "Activation of PI3K-AKT-mTOR pathway can enhance invasion and metastasis ability and reduce apoptosis of LSCC.In addition, Nuclear Factor Kappa B (NF-kB), Carbonyl reductase 1 (CBR1) and CD317 are also popular therapeutic targets for head and neck squamous cell carcinoma." (PMID 31485443, 2019).
lung carcinoma (3 papers, 2017 to 2025). "The role of CBR1 in cancer resistance against five anthracyclines: doxorubicin, daunorubicin, epirubicin, idarubicin, and aclarubicin, was examined in A549 lung cancer cells transduced with the CBR1." (PMID 40629205, 2025). "A549 cell line was chosen because it exhibits low native expression of CBR1 and is relevant to anthracycline-based lung cancer therapy." (PMID 40629205, 2025). "In particular, frequent alteration in GSTT1, ALDH3A3, CBR1 and GSTM3 showed non-redundant events in the three lung cancer subtypes (Z score=2.00, empirical P<0.05)." (PMID 28581523, 2017).
acute lymphoblastic leukemia (2 papers, 2023 to 2025). Leukemia with an acute onset, characterized by the presence of lymphoblasts in the bone marrow and the peripheral blood. "The association of CBR1 with cancer has been extensively studied, especially with the recent discovery of its high expression in Philadelphia-like B-line acute lymphoblastic leukemia." (PMID 37775746, 2023).
Anxiety (2 papers, 2021 to 2024). Intense feelings of nervousness, tension, or panic often arise in response to interpersonal stresses. "In rodents, studies using either antagonists of CBR1, CBR1 knockouts, or injection of endocannabinoids have demonstrated that the endocannabinoid pathway is involved in the behavioural expression of emotions, such as anxiety-like behaviours, during an elevated maze test." (PMID 38374201, 2024).
atherosclerosis (2 papers, 2018 to 2023). A disease characterized by the build-up of fatty material and calcium deposition in the arterial wall resulting in partial or complete occlusion of the arterial lumen. "Activation of CBR2 has been shown to regulate inflammation and may limit the production of oxidized lipoprotein by modulating the effect of CBR1 in the development of atherosclerosis." (PMID 38093188, 2023).
Breast Tumors (2 papers, 2014 to 2021). "CBR1 and CBR2 expression in breast tumours were detectable by IHC." (PMID 34575629, 2021).
cardiomyopathy (2 papers, 2020 to 2025). A disease of the heart muscle or myocardium proper. "For both CBR3-rs1056892 and CBR1-rs9024 variants, carrying the GG genotype along with receiving low-to-moderate doses of anthracycline increased the risk of cardiomyopathy by 3.6-fold compared to AA and GA genotypes." (PMID 40413218, 2025).